FAP (fibroblast activation protein alpha)
Diseases named in the same sentence as FAP in open-access papers (continued):
Sharing a sentence is not in itself a finding about the gene and the disease.
breast carcinoma (continued). "Because of the wide distribution of FAP in numerous cancer types (e.g., sarcoma, prostate cancer, breast cancer, lung cancer, pancreatic cancer, head and neck cancer, colorectal cancer) the question arises whether FAP can be a novel therapeutic target in cancer." (PMID 36813980, 2023). "Similarly, in colon, melanoma, lung, and breast cancer models, exosome-like nanovesicles derived from FAP-engineered tumor cells have been used as a vaccine that inhibits tumor growth by a cytotoxic T lymphocyte (CTL)-mediated immune response against both tumor cells and FAP+ CAFs." (PMID 36338519, 2022). "We also examined the gene dipeptidyl petidease-4 (DPP4/CD26), a close homologue to FAPα, which was recently identified as a fibroblast marker of interlobular fibroblasts in healthy breast tissue and shown to display immune suppressive functions in breast cancer." (PMID 34016130, 2021). "Studies have elicited that FAP-expressing CAFs can demonstrate tumor-forming functions in some cancers such as gastric cancer, but also asporin-expressing CAFs were found to inhibit cancer development in breast cancer, offering two different opportunities for therapeutic intervention." (PMID 33808627, 2021). "Interestingly, the mEnd-IL revealed a higher accumulation in the fibrosarcoma model than in the breast carcinoma model and exposed a relatively similar time-based accumulation pattern like the Bi-FAP/mEnd-IL, but with overall lower fluorescence intensities over time." (PMID 32316521, 2020). "Particularly in human malignancies, FAP expression is often detected on the surface of fibroblasts surrounding epithelial cancers, including pancreatic cancer, colon cancer, prostate cancer, breast cancer and skin cancer, as well as in some bone sarcomas and soft tissues." (PMID 25775399, 2015). "Furthermore, an oral DNA vaccine targeting fibroblasts activation protein (FAP) was developed to suppress primary tumor cell growth and metastasis of multidrug-resistant murine breast carcinoma and allowed reversing resistance to chemotherapy, by increasing intratumoral drug uptake." (PMID 23951052, 2013). "This study analyzed the TCGA database and found that FAP and INHBA were significantly positively correlated with breast cancer." (PMID 41008625, 2025). "According to one study in breast cancer patients, based on the expression of specific markers CD29, FAP, FSP1, α-SMA, CAV-1 and dipeptidylpeptidase 4 (DPP-4, CD26), CAFs can be classified into four subtypes: CAFs-S1 to S4." (PMID 40940764, 2025). "FAP can also be used as a therapeutic target, for example FAPI-04 can be used to target breast cancers with high levels of activated fibroblasts." (PMID 39624628, 2024). "In another work, they also found four CAF populations in breast cancer, but their markers were differentially expressed, CAFS1 and CAFS4 (FAP, CD29, αSMA, PDGFRβ), CAFS2 (αSMA, PDGFRβ), CAFS3 (CD29, PDGFRβ)." (PMID 38606999, 2024). "In breast cancer, CAF markers such as FAP, α-SMA, Vimentin, FSP1, PDGFRα, PDGFRβ, Caveolin-1, and PDPN have been validated." (PMID 39519118, 2024). "A previous study demonstrated that 68Ga-FAPI PET/CT can be used to determine the expression of FAP and further guide 177Lu-FAPI radionuclide therapy in patients with breast cancer." (PMID 38176719, 2024). "The selective depletion of FAP+ cells using NIR-PIT successfully suppressed tumor growth in a subcutaneous mouse tumor model and lung metastasis in a spontaneous mouse mammary tumor model." (PMID 38275890, 2024). "Using CAF-rich syngeneic lung and spontaneous mammary tumors, NIR-PIT against FAP or podoplanin was performed." (PMID 38275890, 2024). "Instead, we chose one syngeneic subcutaneous lung cancer LL/2 and one spontaneously occurring mammary cancer with frequent lung metastasis (MMTV-PyVT GEMM) and investigated the therapeutic and immune effects of FAP-targeted NIR-PIT." (PMID 38275890, 2024).
breast carcinoma (continued). "In vivo anti-FAP NIR-PIT was performed in subcutaneous LL/2, and spontaneously arising MMTV-PyVT mammary tumors to evaluate therapeutic efficacy on tumor growth." (PMID 38275890, 2024). "Recently, an indirect co-culture model and a mixed xenograft of breast cancer demonstrated that TGF-β1-activated CAFs promote tumor invasion, pulmonary metastasis, and EMT, which act through autophagy and overexpression of FAP in both models." (PMID 37316886, 2023). "Exogenous TNF-α has been shown to promote breast cancer cell migration accompanied by an increased secretion of MMP9, as well as upregulate the expression of CD26 and FAP-α in a dose-dependent manner." (PMID 36937451, 2023). "Here, we engineered triple negative MDA-MB-231 human breast cancer cells with FAP-α overexpressed, to understand the role of FAP-α in cancer cell metabolism using 1H magnetic resonance spectroscopy (MRS)." (PMID 36937451, 2023). "We show that FAP is selectively expressed by MSCs and can be used as a potential marker for the identification of BCC-engulfing MSCs in breast cancer tissues." (PMID 37607007, 2023). "FAP-directed 90Y-FAPI and 177Lu-FAPI RLT has been reported previously in several tumor entities (e.g., sarcoma, pancreatic adenocarcinoma, and breast cancer)." (PMID 37024301, 2023). "Administration of oral FAP DNA vaccine induced CD8+T cell–mediated killing of CAFs and successfully suppressed primarytumor growth and colon and breast carcinoma metastasis in multidrug-resistant murine models." (PMID 37784082, 2023). "Then, we analyzed, with a Real-Time PCR, the expression of two important CAF markers, such as FAP and SPARC (or osteonectin), in primary BCAFs and paraffin-embedded breast cancer tissues." (PMID 35743318, 2022). "Targeting of CAFs using a DNA vaccine directed on the FAP demonstrated tumor suppression and reduced the potential for metastasis in CRC and breast cancer models." (PMID 33806802, 2021). "These analyses demonstrate that all six markers identify CAFs in breast cancer, and we therefore designed an antibody panel consisting of the 5 cell surface CAF markers: FAPα, PDGFRα, PDGFRβ, PDPN and CD26." (PMID 34016130, 2021). "In human breast cancer, the only CAF population suggested to express high levels of FAPα and CD26 is the immune suppressive CAF-S1 population." (PMID 34016130, 2021). "Several approaches have been applied on the targeting of CAF-related surface markers, such as FAP and α-SMA, since they are highly expressed in a number of tumour tissues, including pancreatic, lung, and breast cancer." (PMID 33806468, 2021). "In case of breast cancer model, it has to be noted that MCF-7 breast tumor cell line was FAPα−negative but ultimately formed tumors that exhibited positive FAPα expression." (PMID 30871158, 2019). "A fortunate pre-clinical exception is the use of a DNA-based FAP vaccine, which showed an excellent anti-stromal CD8-mediated immunity, with subsequent restoring of chemosensitivity in a mouse model of breast cancer." (PMID 30871158, 2019). "The FAP-a protein expression was mainly detected in the cytoplasmic fractions of stromal fibroblasts, while GOLPH3 in was detected the cytoplasm of breast carcinoma cells." (PMID 31921678, 2019). "Two breast cancer cell lines, Hs578T and SKBR3, representing FAPα + CTCs (CTCFAPα) and EpCAM + CTCs (CTCEpCAM), respectively, were chosen to evaluate cell recovery and cross-reactivity using the dual selection strategy." (PMID 29657983, 2017). "FAP α is expressed by more than 90% of human epithelial tumors, and there has been much interest in exploring FAP α as a therapeutic target in breast cancer." (PMID 26985769, 2016). "To assess this prediction, we isolated mammary tumors from female MMTV-PyMT mice and performed immunostaining for collagen, and dual staining for FAP, SR-A that would indicate co-localization of TAFs and TAMs, respectively." (PMID 26934296, 2016).
breast carcinoma (continued). "In addition, FAP could be an indirect target of the TGFβ signaling pathway in breast cancer." (PMID 25816202, 2015). "In the in vitro cell growth assay, it was observed that a significantly higher rate of growth was achieved in FAP-α transfected MCF7 cells, but that there was little change in MDA-MB-231 breast cancer cell growth." (PMID 24885257, 2014). "We primary cultured CAFs and NFs from early stages of breast cancer tissue and identified them using their biomarker by immunohistochemistry for Fibronectin, α-SMA and FAP." (PMID 23577100, 2013). "The plotted deconvolution results obtained from Cell2location showed high agreement with the CTA on the same breast cancer sections, which was further supported by the spatial expression of cell type markers (i.e., PTPRC for immune, FAP for stroma, and EPCAM for tumor) in the same tumor regions." (PMID 40925915, 2025). "As a monotherapy, FAP-RLT is well tolerated with manageable side effects, showing encouraging response to tumors with high levels of FAP expression, such as sarcoma, PDAC, breast cancer, RR-DTC, and lung cancer." (PMID 41425958, 2025). "Interestingly, the breast cancer cell-derived exosomes Exo-MCF-7 and Exo-MDA-MB-231 induced increased expression of α-SMA and FAP in fibroblasts, and the potency of Exo-MDA-MB-231 was greater than that of Exo-MCF-7." (PMID 40151143, 2025). "We verified FAP protein expression in select cancers through the UALCAN platform, observing elevated levels in tumors like COAD, KIRC, Lung adenocarcinoma (LUAD), and Breast cancer." (PMID 39055892, 2024). "The increased FAP expression promoted ductal carcinoma that would not be otherwise promoted in the absence of FAP in breast cancer." (PMID 39579201, 2024). "Moreover, TIMER2.0 analysis confirmed higher endothelial cell content in FAP-positive tumor samples of cancer entities such as colon adenocarcinoma (COAD) and breast cancer (BRCA)." (PMID 36672341, 2023). "Similarly, TGF-β1 can trigger the activation of CAFs in breast cancer; activated CAFs promote tumor invasion, metastasis, and EMT by inducing autophagy and overexpressing FAP." (PMID 37461061, 2023). "It has been hypothesized that positron emission tomography (PET) of radiolabeled FAP inhibitors (FAPI) with short-living positron emitters (e.g., 68Ga/18F) may replace 18F-FDG in several major tumor types (e.g., breast cancer, pancreatic cancer, sarcoma)." (PMID 36813980, 2023). "Concomitant analyses of six biomarkers, including FAP, CD29 (integrin-β1), α-SMA, FSP1, PDGFRβ, and caveolin, characterized four CAF subsets (from CAF-S1 to CAF-S4) with distinct properties in ovarian and breast cancers (BC)." (PMID 37784082, 2023). "FAP vaccination has been attempted in several studies, in which tumor growth and metastasis were suppressed and survival time was prolonged, and there was increased infiltration of CD8+ T cells in a murine model inoculated with colon or breast cancer cells." (PMID 34068501, 2021). "Analysis by flow cytometry showed binding of the αEpCAM–αCD3 and αEpCAM–αCD28 BiMAb to EpCAM-positive MCF-7 breast cancer cells, whereas irrelevant FAP-specific BiMAb did not bind, as this antigen was not expressed on MCF-7 cells." (PMID 34484225, 2021). "However, the complexity of FAPα-positive CAFs is emphasised by the identification of 8 clusters of the FAPα-positive CAF-S1 population exhibiting distinct signatures, which differentially accumulated in different breast cancer subtypes." (PMID 34016130, 2021). "In this context, FAP+ breast cancer cells do not exhibit in vitro proliferation advantages, although inoculation into severe combined immunodeficiency mice leads to faster tumor growth and a higher degree of vascularization." (PMID 34490078, 2021). "The strength of this study is that they isolated BCAFs from breast cancer patients and characterized them using Vim, FAP and the absence of an epithelial tumor marker, pan-cytokeratin." (PMID 34944738, 2021).
breast carcinoma (continued). "A pioneer study has shown oral administration of DNA-based FAP vaccine-induced CD8+ T cell-dependent killing of CAFs, which substantially increase the intratumoral uptake of chemotherapeutic drugs in multi-drug-resistant murine colon and breast carcinoma." (PMID 31462327, 2019). "The expression levels of FAP and ACTA2 in putative CAFs from breast tumors were higher than in fibroblasts from normal tissue, whereas CAV1 expression was lower in putative CAFs from breast carcinoma samples than in fibroblasts from normal tissues." (PMID 28596490, 2017). "Their results showed that PT-630 and LAF-237 did not slow the growth of tumours produced by any of the three breast cancer cell lines expressing FAP-α." (PMID 24885257, 2014). "We analysed the expression pattern of FAP-α in MCF7 and MDA-MB-231 breast cancer cell lines." (PMID 24885257, 2014). "In following in vitro experiments, heterogeneously originated CAFs from breast cancer, colorectal cancer, pancreatic ductal adenocarcinoma and hepatocellular carcinomas, were tested to be sensitive to cell death by hFAP-CAR T cells in vitro, broadening our FAP-CAR T cells use." (PMID 39086477, 2024). "The non-enzymatic function of FAP was found in a breast cancer study, transfection with catalytically inactive FAP in breast cancer cell lines enhanced cell proliferation, migration, and invasion abilities, suggesting that the non-enzymatic activity of FAP also was involved in tumor progression." (PMID 39055892, 2024). "However, in certain cancers, such as breast cancer, CAF-S4 cells show little or no FAP expression but are still associated with the development of metastases, suggesting that FAP is not the sole pro-tumor mechanism related to CAFs." (PMID 39765634, 2024). "Additionally, maytansinoid-conjugated antibody (FAP5-DM1), toxin-conjugated antibody (αFAP-PE38), and FAP inhibitors (e.g., PT630 and PT100) have shown effective FAP-targeted killing in breast cancer and melanoma." (PMID 37784157, 2023). "Moreover, it has been shown that cell growth and motility in breast cancer do not depend on the catalytic activity of FAP, but can be regulated by other signaling pathways." (PMID 37509656, 2023). "In this study, the abundant expression of FAP as determined previously by others through mRNA and protein analyses was confirmed in tumor tissues of diverse origin, including pancreatic ductal adenocarcinoma, sarcoma, CUP, mesothelioma, cholangiocarcinoma, and breast cancer." (PMID 35608703, 2022). "Additionally, the CAF-S1 FAP+ subpopulation is an important source of CXCL12 secretion, which plays a crucial role in resistance to anti-PD-1 and anti-CTLA-4 immunotherapies in pancreatic, ovarian, and breast cancer." (PMID 35745648, 2022). "To further prove the selective binding capability of HFn-FAP nanoparticles, we included in our analysis two additional cellular models of human origin: human-activated myofibroblasts (HMfs), where we previously documented stable FAP overexpression, and the MDA-MB-231 breast cancer cell line." (PMID 33562504, 2021). "We found that the expression levels of FAP-α and α-SMA were significantly up-regulated in invasive breast carcinoma (97.5%, 38 in 39), compared with human ductal carcinoma in situ (DCIS, 33.3%, 7 of 20), suggesting that CAFs facilitated tumor metastasis in patients with breast cancer." (PMID 29325547, 2018). "From our results we conclude that TNF-α-induced activation of the MAPK/ERK signaling pathway may promote breast cancer cell migration via both upregulation of MMP9, CD26 and FAP-α and concentration of these proteases, as also MT1-MMP and MMP2, in the lipid rafts." (PMID 27042827, 2016). "We also found that TNF-α upregulated the expression of the dipeptidyl peptidases CD26 and FAP-α in a dose-dependent manner and, in addition, enhanced the concentration of all five proteases in lipid rafts in the breast cancer-derived cells tested, regardless of cell type." (PMID 27042827, 2016).
breast carcinoma (continued). "Moreover, FAP and MMP could be working together in some cellular environments, as demonstrated by Huang and collaborators in breast cancer cells." (PMID 25816202, 2015). "A recent investigation suggested that FAP-α promoted tumour growth and invasion of breast cancer cells might be through non-enzymatic functions." (PMID 24885257, 2014). "When using RT-PCR, we found no transcript of FAP-α mRNA in the breast cancer cell lines." (PMID 24885257, 2014). "In our study, a 549 bp product of FAP-α could be amplified in both MCF7exp and MDA-MB-231exp cells while the western-blotting assay of FAP-α protein expression in breast cancer cells showed that a 30 kDa truncate was detected instead of the 97 kDa monomer and 170 kDa dimer." (PMID 24885257, 2014). "Therefore, in this study we analyzed the function of FAP-α in breast cancer cells with the intention to explore the non-enzymatic function of FAP-α." (PMID 24885257, 2014). "However, the selectivity of FAP for stromal fibroblasts, but not epithelial tumor cells, has been confirmed either by immunohistochemical studies in pancreas, colorectal and breast cancer patients, or by RT-PCR of pancreas, lung, and renal cell xenografts." (PMID 21668992, 2011). "Thus, research conducted on a mouse model of breast cancer showed that the introduction of a catalytically inactive mutant form of FAP into cancer cells does not lead to suppression of inoculated tumor growth, although it is necessary for the proteolytic degradation of ECM." (PMID 37509656, 2023). "Consistently, the liposomes accumulated in tumor models originating from human FAP-expressing fibrosarcoma cells and the FAP- and murine endoglin negative breast carcinoma cells at varying levels as could be seen in the differences in fluorescence intensities of the tumors over time post injection." (PMID 32316521, 2020). "Similarly, for early breast cancer, the best three k-gene discriminators are {GPR109B, PCOLCE2, PCSK5}, {PCSK5+COL10A1, FERMT2+SPINT2, MAOA+IGJ}, {COL1A1+PCSK5+TF, GPX3+COL1A1+SPINT2, GPX3+FAP+TMEM97}, and {RRM2+COL1A1+GPR109B+IGJ, RRM2+COL1A1+GPR109B+IGJ, RRM2+COL1A1+GPR109B+SPINT2}, respectively." (PMID 21060876, 2010). "This can be attributed, particularly in breast cancer, to the presence of two subpopulations of CAFs within the lymph nodes: CAF-S1, which overexpresses FAP, and CAF-S4, which does not express FAP." (PMID 39765634, 2024). "Unlike mesenchymal markers such as αSMA, fibroblast-specific protein 1 (FSP1), and fibroblast activation protein (FAP), NR2F1 has not been described to be highly expressed in breast cancer CAFs." (PMID 35740627, 2022). "We isolated 12 pairs of primary CAFs and corresponding NFs from breast cancer and noncancer tissues, and the purities of CAFs were identified by the activated fibroblast biomarkers α-SMA, FAP and vascular endothelial marker CD31 (a biomarkers of endothelial cells as control) as previously reported." (PMID 33754039, 2021). "Some studies have suggested that FAP-α is expressed by stromal cells rather than cancer cells in epithelial malignant diseases; however other studies have demonstrated that FAP-α is also expressed in epithelial malignant cells such as breast cancer, gastric carcinoma, and cervical carcinoma." (PMID 24885257, 2014).